C3orf38 (chromosome 3 open reading frame 38)
Description:
May be involved in apoptosis regulation.
Synonyms: MGC26717
Tractability: Antibody: the Human Protein Atlas places it where antibodies can reach. PROTAC: ubiquitination databases record sites on it.
Gene: Protein-coding gene on chromosome 3 (88,149,647 to 88,168,729, forward strand). Ensembl gene ENSG00000179021.
Subcellular location (Human Protein Atlas): Cytosol; Plasma membrane; Nucleoplasm
Gene Ontology:
Biological process: positive regulation of apoptotic process
Cellular component: nucleus
Genetic constraint (gnomAD): Loss-of-function variants: 20 observed, 31.59 expected, observed/expected ratio (o/e) 0.63, 90% interval 0.44 to 0.92. The upper end of that interval is the gene's LOEUF score, 0.92, which puts it in group 3 of 6, group 1 being the genes least tolerant of losing a copy. Missense variants: 364 observed, 416.24 expected, observed/expected ratio (o/e) 0.87, 90% interval 0.8 to 0.95. Synonymous variants: 145 observed, 146.41 expected, observed/expected ratio (o/e) 0.99, 90% interval 0.86 to 1.14.
Homologues: Orthologues: chimpanzee C3H3orf38 (99% identical), macaque C2H3orf38 (95% identical), rabbit C3orf38 (88% identical), pig C3orf38 (85% identical), mouse 4930453N24Rik (84% identical), rat C11h3orf38 (84% identical), dog C33H3orf38 (83% identical), rat Cxh3orf38 (83% identical), guinea pig C3orf38 (81% identical), rat AABR07000292.1 (67% identical), zebrafish C9H3orf38 (43% identical), tropical clawed frog c2h3orf38 (40% identical), and 1 more.
Diseases named in the same sentence as C3orf38 in open-access papers:
C3orf38 is named in the same sentence as 1 disease in open-access papers, as found by Europe PMC text mining. Sharing a sentence is not in itself a finding about the gene and the disease. The quoted sentences say what the papers report.
Obesity (1 paper, 2019). Accumulation of substantial excess body fat. "In all three discovery analyses, in addition to loci mapping to established BMI and obesity loci, we identified PIGZ and C3orf38, two putative novel loci in the thin vs control analysis, that reached conventional genome-wide significance (GWS) (p≤5x10-8)." (PMID 30677029, 2019).